IGF1 (insulin like growth factor 1)
Diseases named in the same sentence as IGF1 in open-access papers (continued):
Sharing a sentence is not in itself a finding about the gene and the disease.
tumor (continued). "Surgical results are dependent on the preoperative serum GH and IGF-1 levels, extent of tumor invasion, and the skill of the neurosurgeon." (PMID 28874187, 2017). "In our analysis of IGF-1R β degradation in cells grown under serum deprivation with exogenously added IGF-1 we observed decreased degradation upon compound treatment as compared to effects in tumor cells grown in serum conditions." (PMID 27384680, 2016). "The success rate of post-surgical somatostatin analogue therapy, in terms of normalized IGF-1 and reduced GH levels, correlated with the amount of tumor removed surgically." (PMID 26290466, 2016). "The EBERs are ligands of TLR3 and there is evidence that their stimulation supports tumor growth through an increase in insulin-like growth factor 1 (IGF-1) expression." (PMID 27791989, 2016). "IGF-1 levels after treatment were the best predictors of tumor shrinkage, followed by GH levels and age." (PMID 26290466, 2016). "Plasma levels of GH and/or IGF-1 are thereby controlled and any bulk effects of the tumor removed or minimized." (PMID 26290466, 2016). "GGI, a gene signature that mainly measures tumor proliferation, was highly correlated with Oncotype DX, Gene70, modules describing proliferation (AURKA) and PTEN loss, and MYC and IGF1 pathway activation." (PMID 26934123, 2016). "In the absence of IGF1 administration, spleen enlargement was significantly decreased in EphA4‐KO tumor‐bearing mice, and IGF1 treatment was able to markedly increase splenic enlargement of EphA4‐KO tumor‐bearing mice." (PMID 26923183, 2016). "CCL5 and IGF-1 specific staining was detected in peritumoral adipocytes of TNBC samples (up to 1 cm distance from the tumour)." (PMID 27027351, 2016). "We also found that the IGF1 rs5742714 polymorphism was an independent prognostic predictor of RCC survival, along with clinical stage and tumor grade, in multivariate analysis." (PMID 27976731, 2016). "In view of this, a better understanding of the limited role of IGF1 or IGF1R in regulating tumor progression will potentially re‐evaluate their functions." (PMID 26923183, 2016). "They further find that silencing TRIB3 not only decreases the basal levels of critical tumor‐promoting factors, but also protects them from the IGF‐1 induction." (PMID 27038142, 2016). "The decreased IGF-1 and leptin and the increased adiponectin levels in genetically engineered models reflect the significantly superior tumor inhibition of ICR compared to CCR." (PMID 27653140, 2016). "EphA4 appears to have multiple pathways in regulating tumor development beyond IGF1 synthesis, such as the EphA4–FGFR pathway." (PMID 26923183, 2016). "Constitutive activation of IGF-1 downstream mediators renders the tumor cell irresponsive to fasting-induced cellular protection." (PMID 27282289, 2016). "Goals of treatment are amelioration of clinical signs and symptoms, reduction of morbidity and mortality, and control of GH and IGF-1 hypersecretion and tumor growth." (PMID 26603536, 2016). "In turn, the release of bone-derived growth factors (transforming growth factor β (TGFβ) or insulin-like growth factor 1 (IGF-1)) and calcium (Ca2+) from resorbed bone promote tumour growth." (PMID 27782035, 2016). "The plasma level of IGF1 was significantly lower in Epha4‐KO tumor‐free mice compared with ‐WT tumor‐free mice.Similar results were found in tumor‐bearing mice." (PMID 26923183, 2016). "Therapeutic strategies are therefore aimed at removing tumor mass and/or stabilizing tumor growth while maintaining pituitary function, as well as normalizing the effects of growth hormone (GH) and insulin-like growth factor 1 (IGF-1) at target tissues." (PMID 26290466, 2016). "Significant tumor volume reduction (≥30 %) was documented in five patients, and all 22 had significant reductions in GH and IGF-1 levels." (PMID 26290466, 2016). "The levels of human IGF1 protein in mouse serum were observed to be significantly increased in hGH or hPRL expressing tumor bearing mice." (PMID 27102295, 2016).
tumor (continued). "To gain some insight into how prolonged feeding with HFKD promotes tumor growth, we measured the plasma insulin, IGF-1 and growth hormone levels." (PMID 26892894, 2016). "Combined IGF1R and AXL inhibitors are required to block the PSC-induced tumor cell phosphoproteome—suggesting a Boolean “OR” axis between PSC IGF1/GAS6 and PDA pAKT." (PMID 27087446, 2016). "Another possibility is the autocrine stimulation of the tumor by Gh, resulting in increased Igf-1 secretion in the circulation." (PMID 27706259, 2016). "The additive or synergistic effects of IGF1 and E2 on cell proliferation, tumor development, anti-apoptosis and vascular protection have been well described." (PMID 27072650, 2016). "The advantages of surgery include immediate lowering of GH and, subsequently, IGF-1 levels, elimination of the local mass effects of the tumor, and tissue sampling for analysis." (PMID 26290466, 2016). "To investigate the effect of IGF1 treatment and tumor growth on plasma level of IGF1, we analyzed plasma IGF1 level of tumor‐bearing mice compared with tumor‐free mice by ELISA assay." (PMID 26923183, 2016). "The goals of treatment are to ameliorate symptoms, reduce morbidity and mortality, and control GH/IGF-1 hypersecretion and tumor growth." (PMID 26377024, 2016). "Our results demonstrated that the regulation of tumor development by IGF1 was mainly for the enhancement of tumor growth." (PMID 26923183, 2016). "Tumor cell migration is mainly stimulated by various growth factors, such as insulin-like growth factor-1 (IGF-1), epithermal growth factor (EGF), hepatocyte growth factor (HGF), and basic fibroblast growth factor (bFGF)." (PMID 27363031, 2016). "PARP cleavage was induced, and IGF-1 shown to reduce PARP cleavage to barely detectable levels in these metastatic tumor cells." (PMID 27437872, 2016). "High IGF-1 and insulin levels in the microenvironment therefore provide a plausible mechanism of carcinogenesis and early tumor growth through anti-apoptotic signaling and metabolic reprogramming mediated by the PI3K–AKT–mTORC1 pathway." (PMID 26878387, 2016). "GHRH can stimulate tumor growth through the GHRH/GH/IGF-1 axis and local GHRH stimulatory loops between GHRH and its receptor." (PMID 27774107, 2016). "Our data indicate that the highly mitogenic compounds, insulin X10 and IGF1, which both stimulate the IGF1-receptor, significantly decreased the latency time for tumor development." (PMID 25848982, 2015). "Conversely, CR diet exhibited less tumor burden with a significant reduction in levels of insulin, IGF-1 and inflammation markers." (PMID 25895126, 2015). "Different from IGF1, IL-1β is a very classical NF-κB activating cytokine, which is frequently found in the tumor environment." (PMID 26318844, 2015). "The average tumor weights and serum IGF-1 levels in BxPC-hmIGF1-injected mice were significantly higher than those in BxPC-mock-injected mice." (PMID 25638159, 2015). "In this scenario, it is most likely, that IR-A functions as the main IGF-2 receptor, as the IGF-1R is often saturated by the high levels of IGF-1 of tumor microenvironment." (PMID 25798130, 2015). "Insulin-like molecules with strong mitogenic signaling, insulin X10 and IGF1, significantly decreased the time for tumor development." (PMID 25848982, 2015). "Biased agonism and the binding of IGF1 to the integrin β3 receptor are novel mechanisms of tumor resistance to anti-IGF1R antibodies that we will discuss below." (PMID 25699021, 2015). "The administration of IGF-I in vivo increases the growth of tumors while decreases in IGF-1 levels results in a reduction of tumor growth." (PMID 26061745, 2015). "In this study, we demonstrate that metabolic stresses including insulin/IGF-1 enhance expression of TRB3 in a diversity of human tumour tissue and cells." (PMID 26268733, 2015).
tumor (continued). "IR-A overexpression and enhanced IGF-1/IGF-2 autocrine/paracrine production often coexist in several malignancies and is associated with an aggressive and dedifferentiated tumor phenotype." (PMID 25798130, 2015). "IGF1 expression varied by tumor grade: IGF1 positivity was higher in well-differentiated and moderately differentiated tumors (33%) compared to poorly differentiated and undifferentiated tumors (17%) (P = 0.009)." (PMID 25619494, 2015). "All available clinical information was recorded including: age, initial and last percentage of the upper limit of normal (%ULN) IGF-1 levels, comorbidities and other neoplasms (benign and malignant)." (PMID 25996963, 2015). "Several animal studies showed that PCa xenograft mice fed with HFD had more increased tumor growth and shorter survival time, accompanied with higher serum insulin and IGF-1 levels." (PMID 25722971, 2015). "The insulin/igf1 pathway has been shown to be involved in mammalian regulation of lifespan and tumor growth." (PMID 26647160, 2015). "MCF-7 cells stably overexpressing IGF-1 induce significantly higher tumor volumes compared with control or mock cells in mouse xenografts." (PMID 25743390, 2015). "In a group of 30 newly diagnosed acromegalics, pre-surgical treatment with lanreotide autogel for 24 weeks induced tumor shrinkage ≥20% in 79% (23/29) and resulted in mean GH <1 μg/L and IGF-1 normalization in 33.3% (10/33) of the patients." (PMID 26918140, 2015). "Further, blockade of the IGF1R with antibody can promote IGF1 signaling through the integrin β3 receptor in tumor cells." (PMID 25699021, 2015). "Animal models support the participation of the GH/IGF-1 axis in the development of neoplasms, both in tumor growth and metastases." (PMID 25996963, 2015). "The altered phosphorylation of Akt and mTOR in HED and CRD tumors correlated with the corresponding levels of insulin and IGF-1 and the tumor growth observed in the respective groups." (PMID 25026276, 2014). "Using qRT-PCR demonstrated that IGF-1 expression was downregulated >2-fold in 90% (26/29) of tumor tissues examined." (PMID 24586785, 2014). "Leptin promotes tumor growth, eliciting the activity of several signaling pathways such as insulin-like growth factor-1 (IGF-1) and HER2 and inducing the expression of MMP-2, MMP-9, and VEGF, which finally promote cell migration and metastatic spreading." (PMID 25136593, 2014). "Most of these studies have attributed the tumor inhibitory effect of CR to the deceased circulating levels of insulin and IGF-1 and inhibition in its subsequent downstream signaling of PI3K/Akt-mTOR." (PMID 25026276, 2014). "In androgen-independent PCa, IGF1 induces tumor cell motility by activation of αvβ3 integrin via the PI3-K/Akt pathway." (PMID 24708576, 2014). "Because of the lack of a control group not receiving therapy, it was uncertain that the better survival outcomes of high IGF-1 group resulted from better tumor prognosis or better therapeutic efficacy, or both." (PMID 24586785, 2014). "In in vivo preclinical studies, it has been reported that IGF1 messenger levels are lower in the liver tumour tissue than in the tumour-surrounding tissue or healthy liver tissue of mice harbouring HCC." (PMID 25225571, 2014). "Extrasellar tumor growth, mixed tumors (GH- and prolactin-secreting), dural invasion, tumor size, cavernous sinus invasion, Knosp grade, and pre-operative GH and IGF-1 levels have all been shown to be predictors of poor surgical outcome." (PMID 24293348, 2014). "Comparing the CRD and RD groups, it can be suggested that the main tumor regressive effects of CRD are associated with decreased production of insulin, IGF-1 and leptin." (PMID 25026276, 2014). "Insulin down-regulates expression of insulin-like growth factor-binding proteins within the breast, increasing the bioavailability of IGF-1 and stimulating tumour development." (PMID 25338520, 2014).
tumor (continued). "Higher IGF-1 expression in liver adjacent to tumor was associated with poorer median survival of 22 months, compared with 72 months with equal or lower IGF-1 expression in adjacent liver relative to tumor (P = 0.006)." (PMID 25052889, 2014). "The idea that tumor-specific factors also contribute to the decline of IGF-1 in HCC was supported by evidence that overexpressed miR-190b in HCC tumor tissues regulated IGF-1 expression." (PMID 24586785, 2014). "Last, disruption of IGF-1 signaling in several mouse models mimics many of the effects of CR including, increased maximum lifespan, reduced tumor progression, delayed cellular replicative senescence and reduced rates of cell proliferation." (PMID 25369265, 2014). "CR in rodents reduces IGF-1/insulin–PI3K–Akt–mTor signaling which has been shown to be correlated with significant tumor growth delay." (PMID 24436017, 2014). "Our results demonstrate that tumor stromal cells contribute in the physiopathological response to IGF-1/IGF-1R." (PMID 25095896, 2014). "Excess body weight is related to higher level of insulin and insulin-like growth factor I (IGF-1) which promote certain types of tumor cell proliferation and growth." (PMID 25198347, 2014). "In a murine colon cancer model, CR reduces tumor burden through IGF-1–dependent reductions in NF-κB signaling." (PMID 24804677, 2014). "One pathway that has emerged in breast, pancreas, prostate, skin, and other tumor model systems is the insulin-like growth factor-1 pathway (IGF-1)." (PMID 24732966, 2014). "In this study, miR-223 was shown to directly bind to IGF-1R and repress IGF-1 signaling cascade including AKT/mTOR/p70S6K suggesting that miR-223 functions as tumor suppressor through the suppression of IGF-1R-mediated cell growth signaling." (PMID 25628647, 2014). "For example, rapamycin suppresses IGF-1 stimulated F-actin reorganization and migration in various tumor cell lines by inhibiting mTORC1 activity." (PMID 24605059, 2014). "The obese animals which had increased levels of IGF-1 had corresponding increases in proliferation in the tumor and decreases in apoptosis suggesting an activation of the IGF-1 pathway." (PMID 24732966, 2014). "Given the breadth of evidence implicating IGF-1 in neoplasia, several preclinical and clinical attempts have been made to develop target therapies towards IGF-1 Receptors and downstream effectors such as PI3K/Akt." (PMID 25062088, 2014). "The patient had a striking response to pharmacological treatment with combined SSA and dopamine agonist therapy in terms of GH/IGF-1 and prolactin normalization, as well as reduction in tumor volume." (PMID 24166706, 2014). "The clinical features of the disease occur because of the peripheral effects of excessive GH and IGF-1, as well as tumor pressure." (PMID 25511633, 2014). "Consistent with the established role of IGF1 in supporting tumour cell proliferation, neutralising antibody-directed blockade of the IGF1-R in each of the NSCLC cell lines tested resulted in a partial inhibition of proliferation." (PMID 23826179, 2013). "Inflammatory mediators are also involved in the regulation of various growth factors and hormones, including VEGF (vascular endothelial growth factor) and IGF-1 (Insulin-like growth factor-1), which are involved in tumor cell proliferation and metastasis." (PMID 23675573, 2013). "The relative increased expression of INSR (a receptor for insulin) and IGF1 in the resistant cohort in our study indicates that the drug resistant cells evolve multiple compensatory mechanisms for tumour cell survival." (PMID 24237932, 2013). "For example, klotho is observed to induce cell apoptosis and inhibit tumor growth through inhibiting insulin/ insulin-like growth factor-1 (IGF-1) signaling." (PMID 23432957, 2013). "Klotho is observed in several tumors to induce cell apoptosis and inhibit tumor growth through inhibiting insulin/IGF-1 signaling by inhibiting the tyrosine phosphorylation of IGF-1 receptor." (PMID 23432957, 2013).
tumor (continued). "We therefore characterized the MC38 cell line used for the allograft studies extensively and performed a series of animal experiments to obtain a reliable estimate of the possible tumor growth-promoting effect of HI, X10 and IGF-1 in vivo." (PMID 24260289, 2013). "Except for experiment A, a trend towards increased tumor growth after treatment with HI, X10 and IGF-1 was observed in all experiments, and the fold change in tumor growth were generally of approximately similar magnitude for each type of treatment." (PMID 24260289, 2013). "Results showed that CR alone decreased final tumor weight, plasma insulin and IGF-1 levels, and increased apoptosis." (PMID 23823800, 2013). "This is thought to be secondary in part to IGF-1 chemoattraction from bone stromal cells, allowing for a microenvironment that is conducive to tumor growth." (PMID 23383402, 2013). "In fact, treatment with IGF-1 stimulated tumor growth significantly more than treatment with HI and X10." (PMID 24260289, 2013). "This represents an innovative demonstration of growth-promoting effects of X10 and IGF-1 on neoplasms in short-term experiments using obese and hyperinsulinemic animals." (PMID 24260289, 2013). "We used these supra-pharmacological doses of insulin, X10 and IGF-1 because the increased tumor incidence in previous studies was observed after treatment with supra-pharmacological doses of X10." (PMID 24260289, 2013). "In the cixutumumab trial, patients were evaluated for tumor levels of IGF-1, IGF-2, and IGF-1R by immunohistochemistry, and the study reported no apparent correlation between expression of these three proteins and response to cixutumumab treatment." (PMID 23431249, 2013). "An important factor in support of targeting IGF-1R in ES is that EWS-FLI1 acts to suppress transcription of IGFBP3 in tumor cells, thereby resulting in higher levels of circulating IGF-1 and thus increasing activation of the IGF-1R pathway." (PMID 23431249, 2013). "Though the complete mechanism of the anti-tumor effect of CR is far from clear, the plausible involvement of nutrient sensing pathways or IGF-1 pathways proposed for its anti-aging action cannot be overruled." (PMID 22934068, 2012). "PDGFA/PDGFR-α functions via autocrine and paracrine signals to stimulate interstitial hyperplasia and indirectly promote tumor growth; in addition, it can promote cell proliferation by strengthening the response of IGF-1." (PMID 22217202, 2012). "Another highly studied common mediator for the anti-tumor and anti-aging activity of CR is IGF-1 (Insulin Growth Factor 1)." (PMID 22934068, 2012). "Here we reveal through microarray several previously well defined oncogenic and tumor suppressor miRNAs which undergo significant changes in expression following IGF-1 treatment." (PMID 23226206, 2012). "In five studies that prospectively investigated tumour shrinkage during Cabergoline therapy tumour shrinkage was associated with a higher baseline PRL and IGF-1 concentration." (PMID 22550484, 2012). "Once bound to the IGFR1, insulin-like growth factor-1 (IGF-1) acts as a mitogen, augmenting tumor progression through the dual activation of these pathways." (PMID 23226206, 2012). "They involve multiple host and tumor factors, decreased levels of testosterone and insulin-like growth factor-1 (IGF-1), and decreased food intake, contributing to both antianabolic and procatabolic processes." (PMID 23013936, 2012). "Treatment with figitumumab led to the dissociation of IGF1-dependent heterodimeric receptors and inhibited tumor growth with decreased levels of heterodimeric receptors in a mouse xenograft model." (PMID 22438913, 2012).